RELN (reelin)
Diseases named in the same sentence as RELN in open-access papers (continued):
Sharing a sentence is not in itself a finding about the gene and the disease.
depression (continued). "The next sections summarize the research conducted over the years by our group and others, showing the different involvements of reelin in depression and its putative antidepressant properties." (PMID 38255890, 2024). "The goal of this review is to guide future research towards exploring the interplay of reelin in the gut in the pathogenesis of depression." (PMID 38255890, 2024). "Restoring reelin to homeostatic levels has fast antidepressant effects parallel to those of ketamine in animal models of depression." (PMID 38255890, 2024). "Impaired reelin action in the gut likely plays into the discombobulated digestive symptoms that often occur concomitantly with depression." (PMID 38255890, 2024). "Decreased levels of peripheral and central reelin have been observed in schizophrenia, bipolar disorder, and depression." (PMID 38255890, 2024). "Reelin, a protein that is downregulated in patients with depression, appears to work on similar pathways to the antidepressant effects of ketamine." (PMID 37550058, 2023). "Reelin, an extracellular matrix protein released by GABAergic interneurons in adulthood, is downregulated in the hippocampus of patients with depression." (PMID 37550058, 2023). "Attaining a homeostatic balance of reelin, which is known to be downregulated in depression and other neuropsychiatric disorders, is imperative." (PMID 37550058, 2023). "Several other overrepresented neurotransmitters related pathways are synaptic long-term depression (P=7.55E-04) and Reelin signaling in neurons (P=6.00E-03)." (PMID 37747131, 2023). "This is interesting because HDAC inhibitors can reverse stress-induced depression-like symptoms in rodents in a similar way to current antidepressants, which brings more evidence supporting the role of reelin in the pathophysiology of depression." (PMID 35203405, 2022). "In an immunocytochemical analysis of the hippocampal tissues of postmortem patients with major depression, the number of Reelin-positive cells was consistently lower in subjects with major depression than in controls." (PMID 35163751, 2022). "Expression of the reelin gene (RELN) is downregulated in multiple psychiatric disorders, including a decrease in reelin expression levels in the CA4 hippocampal region in major depressive disorder." (PMID 35203405, 2022). "Reelin protein expression in patients with major depression was found to be slightly down-regulated in the molecular layer of the dentate gyrus of the hippocampus." (PMID 35163751, 2022). "Of relevance to the consequences of TBI, hippocampal reelin infusions mitigated depression and cognitive deficits alongside increased hippocampal neurogenesis in a rat model of chronic stress." (PMID 36482407, 2022). "In summary, all these studies indicated a possible important role for reelin in the pathophysiology of depression." (PMID 30930773, 2019). "A further link between ROS and depression has been suggested by recent work focused on the extracellular matrix protein reelin." (PMID 29928190, 2018). "There appears to be a strong link between reelin and neurogenesis in the context of depression-like behavior." (PMID 30374301, 2018). "Although complete loss of reelin signaling is rare in humans, reduced reelin expression has been implicated in multiple neuropsychiatric disorders including ASD, SZ, epilepsy, and depression." (PMID 27364165, 2016). "Co-treatment with antidepressant drugs prevents both RELN deficit and the development of the depression-like phenotype." (PMID 27092053, 2016). "Although many studies of reelin in animal models of depression have focused on the dentate SGZ and adult hippocampal neurogenesis, this is not the only region of the hippocampus where reelin is altered after a period of chronic stress." (PMID 26941609, 2016).
depression (continued). "GABAergic neurons, which are widely distributed in the prefrontal cortex and dentate gyrus (DG) region of the hippocampus, play critical roles in cognition and depression and can secrete Reelin protein." (PMID 27406263, 2016). "As a stress hormone, repeated injections of CORT decreased the number of reelin+ cells in the subgranular zone (SGZ) of the adult dentate gyrus in a preclinical animal model of depression." (PMID 26402670, 2015). "While reelin seems to be involved in the pathogenesis of depression and might have antidepressant effects, research towards the involvement of reelin in the gut and in gastrointestinal dysfunction in depression is limited." (PMID 38255890, 2024). "The results show a single Reelin injection reversed elevated levels of immobility in the forced swim test in both male and female subjects exposed to the cyclic chronic stress model of recurring depressive episodes." (PMID 38482060, 2024). "Secondly, it sought to determine if a single peripheral injection of reelin could effectively mitigate the post-partum depression-like symptoms and neurochemical alterations induced by CORT." (PMID 39228796, 2024). "As reelin is important in the regulation of intestinal stem cell differentiation and crypt–villus migration, lower levels of intestinal reelin in depression likely contribute to the impairment of crypt–villus differentiation and migration processes observed in depressive subjects." (PMID 38255890, 2024). "Depression-induced reduction in gut reelin content may therefore produce weakened neuronal signalling to affect overall gut function." (PMID 38255890, 2024). "Moreover, in a chronic stress animal model of depression where reelin is decreased compared to controls, we observed increases in SERT cluster size that were normalized with reelin treatment both in vivo and in vitro." (PMID 38255890, 2024). "Reelin’s relevance to depression lies in its downregulation in neuropsychiatric disorders and its observed fast antidepressant-like action in preclinical animal models of depression." (PMID 38255890, 2024). "Individuals with depression present with reduced reelin levels, which may contribute to disrupted structural aspects of plasticity, such as alterations to dendritic spine morphology and synaptic stability." (PMID 38255890, 2024). "Importantly, there is also evidence of decreased reelin expression in the dentate gyrus in postmortem samples from patients with depression." (PMID 29515447, 2018). "This evidence indicated that the decreased SGZ reelin expression could bring about a deficit in granule cell maturation, which could be an important event in the pathophysiology of depression." (PMID 26402670, 2015). "The down-regulation of Reelin post ELS may negatively impact hippocampal function, potentially altering stress axis regulation and predisposing to anxiety and depression across the lifespan." (PMID 26583053, 2015). "Based on the summarized literature, we conclude that there might be a role for intestinal reelin in the pathogenesis of depression and that reelin-based therapeutics could serve as a putative novel avenue better targeting the nature of depression at a multidimensional level." (PMID 38255890, 2024). "All in all, we showed that the intravenous injection of the reelin central fragment ameliorates PPD by improving despair-like behavior, as evidenced by a reduction in immobility time in the FST and restored some brain neurochemical alterations associated with depression." (PMID 39228796, 2024). "This review provides a comprehensive overview of reelin’s actions in the gut, delving into the potential molecular mechanisms through which reelin may influence the pathogenesis and treatment of depression, through its actions on the enteric nervous system and the microbiota–gut–brain-axis." (PMID 38255890, 2024).
depression (continued). "The reduction in reelin levels detected in the frontal cortex may be important in inducing the behavioral abnormalities found in this model of depression since such a relationship exists in people with depression." (PMID 38194217, 2024). "Evaluating novel antidepressants like Reelin in a model of recurring depressive episodes helps determine whether the treatment efficacy is impacted by the duration of illness, which varies drastically across individuals seeking treatment for depression." (PMID 38482060, 2024). "Reduced reelin in the gut leads to slowed intestinal cell migration and hindered lining renewal, which may contribute to the digestive issues that commonly accompany depression." (PMID 38255890, 2024). "At the same time, studies on animal models of depression provided numerous evidences that reelin downregulation in the subgranular zone of the dentate gyrus may affect the maturation of dentate newborn neurons and dysregulate the glutamatergic-GABAergic systems crosstalk in limbic brain areas." (PMID 30930773, 2019). "The observation that hippocampal reelin is decreased in patients with depression led our research group to conduct a series of experiments to systematically examine whether reelin is altered in an animal model of depression." (PMID 26941609, 2016). "Moreover, a decrease in reelin levels in the frontal cortex may contribute to impaired synaptic plasticity and the process of neurogenesis and, consequently, the behavioral disturbances observed in depression." (PMID 38194217, 2024). "The importance of investigating potential peripheral mechasims of depression and therapeutics led us to investigate SERT clustering on peripheral lymphocytes, which appears to be influenced by reelin expression as shown in our lab previously." (PMID 32982757, 2020). "Although there has been no direct investigation into intestinal reelin levels in depression, decreases in peripheral reelin have been observed in mood and psychotic disorders." (PMID 38255890, 2024). "Although the administration of reelin has been shown to produce rapid antidepressant effects in the CNS, there is currently a lack of research demonstrating the effects of reelin administration in the ENS in the context of depression." (PMID 38255890, 2024). "We then assessed depression-like behavior using the forced-swim test (FST), cognition using the novel object-location and object-in-place tests, and alterations in hippocampal neurogenesis, reelin, and GABAA receptors using immunohistochemistry." (PMID 29515447, 2018). "In both depression patients and the repeated CORT paradigm our lab has found parallel changes in the analysis of serotonin transporter (SERT) clustering in the plasma membranes of lymphocytes, and thereby we wanted to ascertain the effects of ketamine and reelin on SERT clustering." (PMID 32982757, 2020).
bipolar disorder (52 papers, 2010 to 2025). A disorder of the brain that causes unusual shifts in mood, energy, activity levels and the ability to carry out day-to-day tasks. "Among these were BDNF, VGF, WFS1, DUSP6, CRHBP, MAOA, and RELN, which have previously been implicated in bipolar disorder." (PMID 31114610, 2019). "Abnormal methylation patterns at the RELN gene promoter have been described in post-mortem brains of schizophrenic and bipolar disorder patients." (PMID 27134686, 2016). "Some drugs, like valproate and doxorubicin, can alleviate cognitive deficits and other symptoms observed in SZ and bipolar disorder by inhibiting DNMTs and HDACs and increasing the levels of acetylated histones, leading to an upregulation of reelin expression in a dose-dependent manner." (PMID 26526966, 2015). "Dysfunction of Reelin–Dab1 signaling can lead to behavioral deficits in individuals with SCZ and bipolar disorder." (PMID 40740482, 2025). "The second finding was theimbalance in the allelic expression of RELN in postmortem brains ofschizophrenic patients, but not in controls or bipolar disorder samples." (PMID 21603580, 2011).
Lissencephaly (47 papers, 2007 to 2025). A spectrum of malformations of cortical development caused by insufficient neuronal migration that subsumes the terms agyria, pachygyria and subcortical band heterotopia. "Disruption of RELN signaling causes lissencephaly, a cortical malformation characterized by an abnormal cortical lamination and a loss of the cortical folds due to defective neuronal migration and abnormal cortical layering." (PMID 40924476, 2025). "Patients with autosomal recessive lissencephaly with cerebellar hypoplasia and the mutant reeler mouse harbor homozygous nonsense mutations in the RELN gene, resulting in a complete loss of reelin signaling and the development of lissencephaly." (PMID 40548070, 2025). "RELN variants demonstrate incomplete penetrance and variable expressivity, where biallelic mutations cause severe lissencephaly, while monoallelic variants are linked to increased ASD risk with subtler features." (PMID 40731902, 2025). "The cases we reviewed included lissencephaly, a condition potentially associated with abnormalities in the Reelin protein." (PMID 39452687, 2024). "Collectively, these findings indicate that marked decreases in Reelin protein expression and Reelin signaling cause lissencephaly." (PMID 35163751, 2022). "Mutation of RELN leads to Norman-Roberts lissencephaly in humans and to the reeler phenotype in mice." (PMID 33344456, 2020). "Mutations in REELIN, which encodes a glycoprotein, cause an autosomal recessive form of lissencephaly." (PMID 33381506, 2020). "Mutations in RELN, a gene coding for Reelin, result in a specific lissencephaly, with mental retardation and severe abnormalities of the cerebellum, hippocampus, and brain stem." (PMID 31894918, 2019). "First, loss of function mutations in RELN are associated with lissencephaly (a reduction in cortical folding), and second, the persistence of reelin-expressing Cajal-Retzius cells was observed in patients with polymicrogyria (an excess of folding)." (PMID 30958121, 2019). "Disruption in the Reelin signaling pathway causes disorganized cortical lamination in mice and severe NDDs in human, such as lissencephaly and cerebellar hypoplasia, schizophrenia, bipolar disorder and autism." (PMID 28933765, 2017). "While homozygous loss-of-function mutations of RELN cause lissencephaly with cerebellar hypoplasia [OMIM: #257320], heterozygous missense mutations of RELN cause autosomal-dominant lateral temporal epilepsy (ADLTE) with no brain anomaly." (PMID 28783747, 2017). "An autosomal recessive form of lissencephaly has been associated with the human RELN gene mutations." (PMID 28933765, 2017). "Among them, frontal predominant mild lissencephaly (diffuse pachygyria) with severe hippocampal and cerebellar hypoplasia or Reelin-type lissencephaly is caused by mutation of either RELN or VLDLR and shows autosomal recessive inheritance." (PMID 26052266, 2015). "Mutations in the human Reelin gene are associated with recessive lissencephaly with cerebellar hypoplasia." (PMID 20444278, 2010). "It has recently been reported that VLDLR deletions in humans result in a neurological disorder characterized by lissencephaly and cerebellar hypoplasia, malformations similar but less severe than those associated with RELN deletions." (PMID 17330141, 2007). "Homozygous mutations in the REELIN (RELN) gene also result in lissencephaly, with additional cerebellar hypoplasia." (PMID 17330141, 2007). "Some observations support this hypothesis, apart from the fact that human deficiencies of REELIN or TP73 lead to lissencephaly and mental retardation." (PMID 40498232, 2025). "Interestingly, while loss of reelin is associated with lissencephaly in humans and neuron migration and cortical cerebellar layering defects in mice, overexpression of reelin also causes cortical neuron migration and cortical layering defects." (PMID 39405291, 2024).
Lissencephaly (continued). "Moreover, patients with RELN mutations, leading to low or loss of Reelin expression, show lissencephaly, abnormal neuromuscular connectivity, and congenital lymphoedema that are attributed to Reelin’s absence during development." (PMID 38607022, 2024). "Interestingly, lissencephaly with cerebellar hypoplasia has been attributed to individuals with mutations in CDK5 or RELN." (PMID 38596707, 2022). "In addition to type II lissencephaly with cerebellar hypoplasia, RELN mutations are also associated with autosomal-dominant lateral temporal-lobe epilepsy (ADLTE) with reduced penetrance." (PMID 32962021, 2020). "Mutations in the human REELIN gene induce an autosomal recessive form of lissencephaly characterized by a disorganized neuronal layering, reminiscent to the defects observed in the reeler mouse, and an absence or reduction of convolutions along with cerebellar hypoplasia." (PMID 32604886, 2020). "Lissencephaly and cerebellar hypoplasia, a similar phenotype to that observed in the reeler mutant mice, have been observed in human patients carrying reelin mutations, suggesting that in both rodents and humans, dysregulated Reelin signaling causes neurological defects." (PMID 28507985, 2017). "Homozygous or compound heterozygous mutations in RELN are associated with lissencephaly, but this RELN deletion is the first description of an individual with a developmental phenotype that may be due to haploinsufficiency at this locus." (PMID 24467814, 2014). "In addition, reelin deficiency in human beings leads to lissencephaly, malformations of the hippocampus and cerebellum and severe epilepsy." (PMID 22174859, 2011). "All the decreases discussed in ApoER2/Reelin signaling found in human i3 neurons may contribute to understanding some of the neurological signs in LS; as mentioned patients with lissencephaly due to RELN mutations have a severe delay in cognitive development, hypotonia, and seizures." (PMID 39062513, 2024). "Biallelic variants in RELN encoding Reelin cause lissencephaly and hypoplasia or dysplasia of the cerebellum and hippocampus and heterozygous PAFAH1B1 variants are associated with lissencephaly." (PMID 39085459, 2024). "Disruption of the Reelin gene in humans results in lissencephaly (smooth brain) with clinical systems of severe ataxia, epilepsy and cognitive delay." (PMID 25334023, 2014). "Human LCH, an autosomal recessive form of lissencephaly, has been described in two consanguineous pedigrees (OMIM #257320), and two different variants of the RELN gene were discovered as causal mutations in these patients." (PMID 24260534, 2013). "However, lissencephaly appears with specific phenotypic traits if the reelin pathway is compromised, including anterior predominance lissencephaly, severe cerebellar hypoplasia, and hippocampal abnormalities." (PMID 39040723, 2024). "An impaired Reelin production in the cerebral cortex may lead to cortical abnormalities (e.g., heterotopia, polymicrogyria, and lissencephaly)." (PMID 35422848, 2022). "Some reports have shown spontaneous mutations in RELN leads to lissencephaly and absence of serum reelin." (PMID 35658052, 2022). "The severity of cerebellar abnormality in lissencephaly ranges from discrete midline hypoplasia to disturbed foliation and volume reduction, later being most commonly associated with the involvement the TUBA1A and RELN genes." (PMID 31355197, 2019). "Mutations or deletions in different genes have been identified as involved in lissencephaly cases: the LIS gene is responsible for the autosomal form of classical lissencephaly and the doublecortin gene (DCX or X-LIS) is X-linked whereas homozygous RELN gene has been identified in cases of LCH." (PMID 23938146, 2013). "Moreover, homozygous null mutations of RELN lead to lissencephaly, a disease characterized by the absence of regular convolutions in the cerebral cortex and by cerebellar hypoplasia, neonatal hypotonia, and mental retardation." (PMID 39062513, 2024).